PDGFRA (platelet derived growth factor receptor alpha)
Diseases named in the same sentence as PDGFRA in open-access papers (continued):
Sharing a sentence is not in itself a finding about the gene and the disease.
tumor (continued). "Non-mutated PDGFRa lesions occur in the brainstem, whereas PDGFRa somatic alterations predilect tumor emergence far from the brainstem." (PMID 40361492, 2025). "The G3 tumor also had overexpression of PDGF receptor alpha (PDGFRA)." (PMID 39245631, 2025). "Specifically, PDGFRα overexpression correlated with higher tumor grade and positive nodal status (pN+), while PDGFRβ overexpression was linked to the extent of tumor-associated thrombosis, the presence of distant metastases, and adrenal metastases (P < .05 for all correlations)." (PMID 40434293, 2025). "Overexpression of the studied markers was found to be significantly correlated with high tumor grade (G3-4) (PDGFRα,β) and significant tumor burden: the extent of tumor venous thrombosis (PDGFRβ), pN+ stage (PDGFRα), and M+ stage (PDGFRβ), as well as adrenal metastases (PDGFRβ)." (PMID 40434293, 2025). "Importantly, elevated levels of VEGFB, PDGFRA, MAPK13, and HGF have been previously linked to poor prognosis and aggressive tumor behavior in HCC." (PMID 41002582, 2025). "To investigate whether PDGFRA is the bona fide target of these four mTKIs in the malignant rhabdoid tumour cells, we utilised a gatekeeper mutant of PDGFRA (T674M) that is incapable of binding to the mTKIs33." (PMID 40781553, 2025). "This process occurs through the interaction with other genes such as PDGFRA and HRAS, responsible for encoding an essential subunit of the SWI/SNF chromatin remodeling complex, known for its tumor suppressor function through epigenetic regulation of gene transcription." (PMID 40868137, 2025). "Additional studies demonstrated that Olig2 deletion reduces tumor growth and drives a phenotypic shift from oligodendroglial to astrocytic features, concomitant with PDGFRA downregulation and compensatory EGFR signaling pathway activation, revealing alternative routes for tumor recurrence." (PMID 40428395, 2025). "Tumour cells may immunohistochemically express CD117 and/or DOG-1, and genetic mutations in C-KIT or PDGFRα may be present, which helps differentiate PF from GIST." (PMID 41357577, 2025). "Whereas tumours without any driver-mutation (WT) or with PDGFRA mutations are expected to be imatinib-resistant, tumours with c-KIT mutations are in general imatinib-sensitive." (PMID 41373613, 2025). "We also observed a significant correlation of PDGFRα and PDGFRβ overexpression with high tumor grades (G3-4) and significant tumor burden: the extent of tumor thrombosis (only PDGFRβ), pN+ (only PDGFRα), and M+ (only PDGFRβ) stages, including metastases to the adrenal glands (PDGFRβ)." (PMID 40434293, 2025). "Overexpression of PDGFRα/β was associated with higher tumor grade and advanced RCC stages, though it did not affect patient survival." (PMID 40434293, 2025). "Next, we combined these 3 variables that resulted in an independent association with GIST genotype (SUVmax ≤5.75, gastric location, and tumor size >10 cm) in a clinical score to enhance their accuracy in discriminating PDGFRA-mutant from KIT exon 11–mutant GISTs, assigning 1 point to each of them." (PMID 39853981, 2025). "Importantly, PDGFC induces increased PDGFRA expression in both tumor cells and fibroblasts, which leads to reciprocally positive feedback, accelerating the fibrotic TME and malignant progression of tumors." (PMID 40501228, 2025). "This suggests that PDGFRα may play a central role in epithelial–stromal interactions and influence both tumor and stromal cell behavior through paracrine and possibly autocrine mechanisms." (PMID 40806365, 2025).
tumor (continued). "In PDX tumor tissues, the expression of PDGFRA was reassessed using immunohistochemical analysis." (PMID 40336047, 2025). "This review provides an integrated overview of GBM’s pathophysiology, highlighting key mechanisms such as neuroinflammation, genetic alterations (e.g., EGFR, PDGFRA), the tumor microenvironment, microbiome interactions, and molecular dysregulations involving gangliosides and sphingolipids." (PMID 40868137, 2025). "Together with our findings, these data support a model in which lobular injury, associated with tumor growth, induces a transient NGFR+/PDGFRα+ stromal phenotype in the peritumoral region, distinct from the established cancer-associated fibroblast subtypes characteristic of the desmoplastic stroma." (PMID 41006303, 2025). "In GISTs, FGFR2 expression has been reported at variable levels, particularly in tumors lacking KIT or PDGFRA mutations, suggesting a role in tumor progression independent of canonical drivers." (PMID 41150770, 2025). "Within DHG tumours, patients carrying G34V, rather than R mutations and PDGFRA or EGFR amplification, and lacking MGMT promoter methylation have been associated with the poorest prognosis." (PMID 40986124, 2025). "Moreover, many GBM driver mutations, such as loss of the tumour suppressor PTEN, or amplification of receptor tyrosine kinase-encoding genes, such as EGFR or platelet-derived growth factor receptor A (PDGFRA), can enhance PI3K−AKT−mTOR signalling." (PMID 40977288, 2025). "Integrating scRNA‐seq, next‐generation sequencing (NGS), and multiplex immunofluorescence, our study provides new insights into the potential roles of OPC‐like subpopulations—particularly those expressing EGFR and PDGFRA—in tumor initiation, progression, and lineage transitions." (PMID 41036308, 2025). "Additionally, mutations in the PDGFR-α gene enhance PDGFRα expression, triggering ligand-independent PDGF signaling that fosters tumor growth in NSCLC." (PMID 39737184, 2024). "In summary, the data highlight the importance of these IRGs in both promoting and preventing tumour progression by indicating a strong correlation between the expression level of genes such as LRP1, PI3, PAEP, FOS, FGF7, and PDGFRA and the degree of tumour immune infiltration in OC." (PMID 39063239, 2024). "All three cases with primary PDGFRA D842V mutations had intra-abdomen, not otherwise specified, as the tumor site." (PMID 38473266, 2024). "Tumor regions were selected for scSTA based on high expression of PDGFRA." (PMID 38319732, 2024). "We also found mutation only in the tumor tissue in the genes DICER, ESR1, KIT, PDGFRA, and RAF1." (PMID 38565739, 2024). "Several previous studies showed tumor location was related to the survival of H3K27M‐DMG and the prognosis of patients with infratentorial tumor was poorer than those with supratentorial tumor as well as different molecular alterations such as PDGFRA and FGFR1 between brainstem and thalamus tumor." (PMID 38644565, 2024). "The tumor was found to have an in-frame PDGFRA::USP8 gene fusion." (PMID 38401149, 2024). "In addition, PDGFRA-mutant GISTs tend to have smaller tumour sizes, a lower incidence of metastases and longer survival." (PMID 39070147, 2024). "Conversely, FGF7, FOS, and PDGFRA were less expressed in OC tumour samples than in normal tissues." (PMID 39063239, 2024). "PDGFRA downregulation was observed across the five tumor types analyzed." (PMID 39594421, 2024). "Interestingly, in models of tumor recurrence post-temozolomide treatment, there was a strong selective pressure towards PDGFRA amplification." (PMID 39202398, 2024). "We also analyzed the expression of markers SOX2 and PDGFRA for all tumor types." (PMID 39609428, 2024). "PDGFRA is elevated in several cancers and promotes tumour proliferation, acting as an oncogene." (PMID 38000389, 2024).
tumor (continued). "Subclonal PDGFRA amplification with identical breakpoints was also detected in TG05a (taken post-radiotherapy), suggesting that this subclone was the seeding clone for the grade 4 tumor." (PMID 37932833, 2023). "PDGFRA amplification was detected across broad types of tumor." (PMID 36043552, 2023). "Using BTIC cultures bearing PDGFRA amplification to represent PN subtype GBMs, we found that the tumor suppressive effects of clemastine were accompanied by diminished stemness of tumor cells and altered molecular signatures indicative of more differentiated states." (PMID 37760589, 2023). "Dasatinib exhibited a 71% RR in patients with KIT/PDGFRA wild-type GIST in TKI-naïve patients, while wild-type GIST patients treated with sunitinib in the second-line or beyond exhibited longer PFS compared to patients with KIT exon 11 mutated tumours." (PMID 37627109, 2023). "Both his relapsed cf-tDNA sample and recurrent tumor tissue were detected to have newly emerging CDKN2A:p.L16Pfs*9 and PDGFRA:p.V536E mutations compared to the initial tissue, indicating that the relapsed tumor had evolved more malignant branches featured with CDKN2A loss." (PMID 37920153, 2023). "We also found highly expressed phospho-PDGFRA and phospho-Rb in the recurrent tumor." (PMID 38012788, 2023). "BM-derived MSCs are recruited to breast and lung tumors, differentiate to a distinct subpopulation of CAFs that lack PDGFRα, promote tumor growth and angiogenesis via expression of Clusterin, and end up as a diminished PDGFRα-expressing resident CAFs population." (PMID 37046676, 2023). "Therefore, we isolated the murine PDGFRα+ and F4/80− CAFs at the border of tumor, and co-cultured with EC cells with RB treatment." (PMID 37029408, 2023). "Next-generation sequencing (NGS) assays indicated that the tumor lacked KIT/PDGFRA/SDH/RAS-P (RAS pathways, RAS-P) mutations, thereby classifying this patient as quadruple WT GIST (qGIST)." (PMID 38023229, 2023). "Given that both PDGFRA CNVs and dysregulation of tumor-related pathways are usually present in cancer, we propose that the CN gain of PDGFRA pathway could be a potential target for analyzing cancer-related mechanisms in ACC, KIRC, LUAD, SARC, and UCEC." (PMID 35212838, 2022). "Besides, the qPCR results were consistent with the bioinformatic analysis results in that CAFs expressed a higher level of PDGFRA than other tumor cell lines (all p < 0.001)." (PMID 35378770, 2022). "A strong association between SF3B1 expression and key tumor -markers of development/progression (VEGFA/MKI67/EGFR/CDK4/PDGFRA) was found in GBM (CGGA- and Rembrandt-datasets), but not in the non-tumor samples (Rembrandt-dataset)." (PMID 35086552, 2022). "Furthermore, we investigated the relationships between the CN gain of PDGFRA pathway and tumor-infiltrating immune cell subpopulations in pan-cancerous species." (PMID 35212838, 2022). "Taken together, these studies showed that downregulated PDGFRA may be negatively regulated by STAG1 TF in HCC cells but positively correlated with the emerging vessels surrounding the tumor lesion." (PMID 36052535, 2022). "For example, tumor epithelial cells expressing PDGFA interacted with PDGFRA-expressing fibroblasts." (PMID 34976204, 2022). "Moreover, a recent study revealed that PDGFA/PDGFRα-regulated GOLM1 critically enhances the tumor progression ability through activating AKT signaling in GBM." (PMID 35874629, 2022). "Thus, overexpression and/or hyperactivation of PDGFRA plays a role in the pathogenesis of multiple tumor types." (PMID 34716856, 2022). "Similarly, annotation labels indicated that the ESTIMATE score, immune score, and stromal score of the PDGFRA-high group were greater than those of the PDGFRA-low group, though the opposite result was obtained for tumor purity." (PMID 35378770, 2022).
tumor (continued). "In addition to these genes, they determined that including ATRX knockdown via shRNA resulted in more circumscribed tumors after 4 months, and further addition of PDGFRA to the IUE model shortened the period of tumor growth to 21 days." (PMID 35978801, 2022). "In addition, 4-DAMP significantly attenuated PDGFRα and abolished Axl, both of which play an essential role in tumor angiogenesis." (PMID 36614038, 2022). "To determine whether the upregulation of PlGF was associated with CAF-mediated tumor fibrosis, we analyzed the expression of VEGF family member receptors on PDGFRα+ CAFs." (PMID 36272973, 2022). "Interestingly, over-expression of wild-type PDGFRA, was better at accelerating tumor development than the constitutively active PDGFRA which activated Ras signaling to levels higher than optimal for tumor growth." (PMID 33987182, 2021). "Similarly, we identified that SLUG expression in GIST cells was regulated by paracrine PDGFC secretion by CAFs, which led to PDGFRA signaling in the tumor cells." (PMID 33603171, 2021). "For example, infiltrating oligodendrocytes express high levels of PDGFA that, via activation of its receptor PDGFRα on glioma cells, could fuel tumor proliferation." (PMID 34690699, 2021). "Additionally, reduced PDGFRα expression in tumor tissues derived from Pten−/− MEFs with shPDGFRα was verified by immunoblotting." (PMID 33568640, 2021). "Post-mortem analysis of one GBM with a mosaic pattern of RTK amplifications showed that tumor cells with PDGFRA amplifications were limited to the bulk of the tumor, while EGFR amplifications were observed in the cell population present at areas of infiltration." (PMID 33673104, 2021). "Moreover, the platelet-derived growth factor receptor α (PDGFRA) is uniquely expressed by fibroblasts in the adult heart, and it is dysregulated in a subset of pHGGs and DIPG tumours, driving glioma formation and associated with worse prognosis." (PMID 34831165, 2021). "For USTS the average presence of TEM1 and PDGFRα was 81 and 79% of the tumor samples." (PMID 33535618, 2021). "LncRNAs’ expression profile did not correlate with c-kit and PDGFRA mutation status, as well as age and tumor location." (PMID 34557343, 2021). "Furthermore, the 3D engineered platform indicated that the co-localization of the tumor in the perivascular region was related to the expression of platelet-derived growth factor receptor alpha (PDGFRA)." (PMID 33926127, 2021). "Therefore, in addition to Pten-deficient mouse and human cell lines, the regulatory pathway of PDGFRα by the PTEN-AKT1-CREB axis also existed in human tumor tissues." (PMID 33568640, 2021). "The tumorigenic impact of WT PDGFRA may also be context‐dependent as PDGFRA overexpression with Ink4a/Arf tumor suppressor deletion promotes gliomagenesis." (PMID 34480532, 2021). "Moreover, CM from these CAF cultures increased T1 proliferation, while these effects were abrogated by PDGFC neutralizing antibody, suggesting that PDGFC secretion from CAF lines isolated from KIT and PDGFRA mutant GISTs modulates tumor cell growth." (PMID 33603171, 2021). "Interestingly, MK-1775 alone had a considerable effect on tumor volume compared with vehicle in only the PDGFRA-driven xenografts, indicating inherent cell cycle differences in KIT-driven versus PDGFRA-driven GISTs." (PMID 33320833, 2021).
tumor (continued). "Therefore, we now explore the effects of introducing the EGFR and PDGFRA amplified sub-populations away from the centre of the tumour where there is less competition for space." (PMID 33120534, 2020). "The 729 diagnostic tumor samples that were evaluated with the smMIP panel showed 788 (likely) pathogenic mutations, including mutations that give access to targeted treatment options (e.g. mutations in EGFR, BRAF, MET, ERBB2, KIT, PDGFRA)." (PMID 32264863, 2020). "Moreover, immunofluorescence microscopy revealed that PDGFRA was highly expressed on the cell membrane of CHSY1-overexpressing GL261 tumor tissue sections." (PMID 32019907, 2020). "pIGF1R was most frequently detected in tumor cells expressing both Ki67 and PDGFRα." (PMID 33173731, 2020). "All tested stroma markers with exception of PDGFRa showed a strong correlation with tumor stage." (PMID 31937798, 2020). "Then, PDGFRA D842V substitutions were shown; this tumor was expected to be resistant to imatinib." (PMID 32703220, 2020). "Since the patient data is for the proportions of biopsies containing EGFR and PDGFRA amplified cells above a given density threshold, which we chose to be 10% of the tissue sample, we define an equivalent measure for each simulated tumour by integrating solutions across the whole tissue domain." (PMID 33120534, 2020). "PDGFRα was significantly overexpressed in ADK compared to normal mucosa which may suggest its potential role in the development or the sustain of tumor cells." (PMID 33213472, 2020). "None of these characteristic genetic alterations were observed in the patient tumour or in TK-RIG915 (although high levels of PDGFRA transcript and protein were observed), further supporting that this tumour is distinct from the original diagnosis of primary DIPG." (PMID 33053751, 2020). "We also note that in this work we have avoided modelling single cell events in a macroscopic setting, by assuming that each of the EGFR and PDGFRA amplified sub-populations only become established within a tumour at most once and introduce a small distribution of cells accordingly." (PMID 33120534, 2020). "In addition, nintedanib was recently shown to exert direct anti-tumor effect on tumor cells, but only those with oncogene addiction to growth factors receptors targeted by nintedanib, such as PDGFRα, FGFR2, FLT3, or RET." (PMID 32133285, 2020). "Besides expression of PDGFRα in tumor colorectal cells, we noted the presence of focal to diffuse PDGFRα immunostaining in various mesenchymal stromal cells including inflammatory cells and vessels." (PMID 33213472, 2020). "Finally, we looked at introducing the EGFR and PDGFRA amplified sub-populations in different locations in the growing tumour simulations." (PMID 33120534, 2020). "While this could be the case, a study reconstructing the phylogeny of GBMs identified EGFR and PDGFRA amplification as early and late events during tumour progression." (PMID 33120534, 2020). "Serum amyloid A3 (Saa3) is also identified as new biomarker of mouse PDGFRα+ CAFs in PDAC, as PDGFRα+Saa3+ CAFs could facilitate tumor growth while PDGFRα+Saa3− CAFs impairing tumor proliferation." (PMID 33292666, 2020). "In this case, however, the tumor recurred 6 months after the operation, indicating that overexpression of ALK may play an important role in the early recurrence of GIST harboring PDGFRA mutations." (PMID 32005261, 2020). "Furthermore, a gene signature profile including PDGFRA correlates strongly with the “homing” of tumor cells to the PVN." (PMID 31016107, 2019).